HNF4A (hepatocyte nuclear factor 4 alpha)
Diseases named in the same sentence as HNF4A in open-access papers (continued):
Sharing a sentence is not in itself a finding about the gene and the disease.
diabetes (continued). "Finally, we used this system to compare the P2 wild-type (WT) promoter with the selected P2 variants, shedding light on disease mechanisms of P2-driven HNF4A-MODY diabetes." (PMID 38855865, 2024). "Both population individuals and patients with diabetes manifestations carrying mutations in the HNF4A gene also secrete reduced amounts of insulin in response to glucose and arginine challenge, and have impaired glucagon secretion in response to arginine challenge." (PMID 39902162, 2024). "Variants in GCK, HNF1A, and HNF4A genes are the three main causes of monogenic diabetes." (PMID 40225161, 2023). "We next assessed whether the penetrance of pathogenic GCK variants was influenced by the background rates of diabetes similar to those of HNF1A/HNF4A-MODY." (PMID 36257325, 2022). "HNF4α dysfunction has been associated with metabolic disorders including diabetes." (PMID 35370692, 2022). "Variants in the HNF4A gene seem to be a rare cause of monogenic diabetes in Brazil." (PMID 35592779, 2022). "Finally, Foxa2 has also been implicated in the regulation of Hnf4a and Hnf1a, involved in HI and monogenic diabetes." (PMID 35422763, 2022). "Furthermore, a genomic test is performed by observing the gene encoding glucokinase, HNF1A, and HNF4A, which are associated with diabetes onset." (PMID 34204428, 2021). "Similarly, two gene-specific studies conducted in Tunisia identified two variants, one in HNF4A (from 12 patients with diabetes) and the other in the GCK gene (from 23 unrelated patients with diabetes) respectively." (PMID 34373539, 2021). "Our results provide an excellent opportunity for investigating whether HNF4A-MODY mutations connect clock dysregulation to the development of diabetes." (PMID 34732735, 2021). "CHI within the neonatal period and evolution to diabetes later in life has been reported in individuals with heterozygous inactivating mutations in the hepatocyte nuclear factor 4A and 1A genes (HNF4A and HNF1A) and dominant mutations in ABCC8 genes in a very limited number of cases." (PMID 29739729, 2019). "Mutations in HNF4A are responsible for a syndrome known as Maturity Onset of Diabetes in the Young." (PMID 25209997, 2014). "In addition, features of HNF1A and HNF4A mutation carriers tend to overlap with type 1 diabetes, type 2 diabetes and other monogenic forms of diabetes." (PMID 23803251, 2013). "In humans, HNF4A gene variants are associated with type 2 diabetes mellitus." (PMID 22719926, 2012). "Furthermore, it has been seen before that a mutation can cause opposite effects on insulin secretion in early versus later life, since a HNF4A mutation causes hyperinsulimea in utero and then later causes diabetes in adulthood." (PMID 22073261, 2011). "This gene is interesting in light of findings of increased prevalence of diabetes in schizophrenia, and further investigation of HNF4A variants in schizophrenia may be warranted." (PMID 19772658, 2009). "Thus, in patients with HNF1A/HNF4A mutation, diabetes may present later than before traditionally defined 25 years of age." (PMID 30013516, 2018). "Additionally, genomic mutations in HNF4A could lead to diabetes, a condition frequently associated with NASH." (PMID 29216278, 2017). "This study, the first exploring the relation between HNF4A genetic variants and MetS and metabolic variables in a pediatric cohort, suggests that HNF4α could represent an early marker for the risk of developing type 2 diabetes mellitus." (PMID 25671620, 2015). "Humans with mutations in the genes encoding for the transcription factors Hnf1α and Hnf4α develop similar forms of diabetes that result from abnormal insulin secretion, suggesting that the two factors might have related functions in insulin-producing islet-cells." (PMID 20523905, 2010). "Disruption of these pathways due to HNF4α mutations leads to metabolic dysfunctions such as MODY1, emphasizing its therapeutic relevance in genetic and metabolic forms of diabetes." (PMID 40926269, 2025).
diabetes (continued). "The ClinGen Monogenic Diabetes Variant Curation Expert Panel (MDEP) was established in 2017 and has developed and published gene-specific rules for HNF1A, HNF4A, GCK, and monogenic diabetes, with others in progress." (PMID 41516031, 2025). "ACE2 levels were associated with the loci of diabetes-associated genes HNF1A and HNF4A at GWAS and RVAS." (PMID 41054850, 2025). "Small-molecule agonists and gene therapies aimed at modulating HNF4A activity are being explored for the treatment of diabetes, MASLD, and IBD." (PMID 40926269, 2025). "Mutations in HNF4α are associated with MODY1, a monogenic form of diabetes characterized by β-cell dysfunction, impaired insulin secretion, and progressive hyperglycemia." (PMID 40926269, 2025). "ACE2 levels were increased with a diagnosis of hypertension or diabetes, particularly in females, and were influenced by variants in genes associated with diabetes (HNF1A and HNF4A)." (PMID 41054850, 2025). "HNF4A protein is expressed in various adult tissues, including the pancreas, gut, liver, and kidneys, and defects in HNF4A function can result in diabetes." (PMID 40149950, 2025). "Unregulated diabetes can develop into congenital hyperinsulinism, diabetes mellitus, and diabetic nephropathies, all known to be associated with HNF1A and HNF4A genes." (PMID 39786569, 2025). "VDR agonists, including calcitriol and paricalcitol, are used in chronic kidney disease and osteoporosis, while HNF4A modulators are being studied for diabetes and liver diseases." (PMID 40926269, 2025). "Variants in the genes GCK, HNF1A, HNF1B, HNF4A, ABCC8, INS, and INSR were the main contributors to the genetic pathogenesis of hereditary diabetes mellitus in the Russian cohort." (PMID 39859454, 2025). "Akt-mediated phosphorylation of HNF4A influences pancreatic β-cell function and diabetes pathophysiology." (PMID 40926269, 2025). "In pancreatic β-cells, HNF4A plays a crucial role in insulin secretion and β-cell survival, making it an important factor in diabetes pathophysiology." (PMID 40926269, 2025). "Nineteen patients (63.3%) had a family history of diabetes, including all patients with GCK or HNF4A/1A variants." (PMID 40303944, 2025). "Briefly, loss-of-function variants cause Maturity-Onset Diabetes of the Young type 1 (MODY1; HNF4A-MODY, OMIM #125850); a monogenic form of diabetes characterized by progressive pancreatic β-cell dysfunction and impaired insulin secretion." (PMID 38433330, 2024). "We systematically analyzed evidence for precision treatments for GCK-related hyperglycemia, HNF1A-, HNF4A- and HNF1B-diabetes, and mitochondrial diabetes (MD) due to m.3243 A > G variant, 6q24-transient neonatal diabetes mellitus (TND) and SLC19A2-diabetes." (PMID 39025920, 2024). "We analyzed studies for evidence of SU as an effective glucose-lowering therapy for HNF1A-diabetes and HNF4A-diabetes." (PMID 39025920, 2024). "Similar to HNF1A MODY, the rate of diabetes complications in patients with HNF4A MODY is directly related to glycemic control and is comparable to that of patients with T1D or T2D." (PMID 39408828, 2024). "The interventions on PAQR9, including deletion of PAQR9, caloric restriction and HNF4α activation, are all effective treatments for statin‐induced diabetes, while liver specific over‐expression of PPM1α is another possible tactic." (PMID 38970167, 2024). "Of note, mutations in two members of this family, HNF4A and HNF1A, are known to cause Maturity Onset Diabetes of the Young (MODY) – MODY1 and MODY3 respectively." (PMID 38909044, 2024). "There were 12 studies that contributed to data on treatment for GCK-related hyperglycemia, 23 studies for HNF1A-diabetes, and three studies for HNF4A-diabetes (with several studies contributing data to more than one diabetes subtype)." (PMID 39025920, 2024). "By contrast, GIGYF1, HNF1A and HNF4A are involved with lower level cellular processes which have a less immediate impact in terms of producing diabetes as a phenotype." (PMID 39666780, 2024).
diabetes (continued). "Benfluorex used to be a clinical diabetes medicine by activating HNF4α, which also improved levels of insulin and FFA affected by atorvastatin treatment, as well as fasting glucose." (PMID 38970167, 2024). "What is the optimal glucose-lowering therapy in the three commonest subtypes of autosomal dominant familial diabetes (MODY): GCK-related hyperglycemia, HNF1A-diabetes, and HNF4A-diabetes?" (PMID 39025920, 2024). "We focused our efforts primarily on pancreatic beta cells and secondarily on hepatic cells, as these cells are central to diabetes biology and provide a biologically relevant context for the study of HNF4A and HNF1A." (PMID 38909044, 2024). "There are no studies on drug-naïve newly-diagnosed patients with HNF1A- or HNF4A-diabetes comparing the different treatment options." (PMID 39025920, 2024). "As HNF4A is known to be involved in pancreatic beta cell development and function, and defects in HNF4A function can lead to diabetes, we next asked what gene targets downstream of HNF4A contribute to the regulation of beta cell function." (PMID 38909044, 2024). "Improved insight into the mechanism of disease has been important to enable precision diabetes treatment for several of these disorders, e.g., sulphonylurea agents for the treatment in K-ATP neonatal diabetes, HNF4A-MODY, and HNF1A-MODY." (PMID 38855865, 2024). "In another study, patients diagnosed with early type 2 diabetes were examined for mutations in the HNF1A, HNF4A, and GCK genes; a monogenetic form of diabetes was diagnosed in 4%." (PMID 38550917, 2024). "Although in Europe HNF4A-MODY, GCK-MODY, and HNF1A-MODY, carry the most common pathogenic variants, accounting for > 80% of all monogenic diabetes, in the MENA region, MODY prevalence is mainly unexplored." (PMID 39191897, 2024). "In 1996, HNF4A was identified as the gene mutated in Maturity Onset Diabetes of the Young 1 (MODY1), an inherited form of type 2 diabetes that causes diabetes in patients in young adulthood." (PMID 37600688, 2023). "For monogenic diabetes in clinically unselected cohorts, pathogenic variants in GCK display near-complete penetrance, while variants in HNF1A and HNF4A show reduced penetrance." (PMID 37285546, 2023). "The molecular diagnosis of MODY has substantial implications for the management of diabetes, and individuals with HNF4A-MODY are optimally treated with low-dose sulfonylureas." (PMID 37711893, 2023). "Genetic evaluation of a teenager with seizure found no pathogenic variant in a large gene panel, but an incidental likely pathogenic HNF4A variant, deemed to cause MODY1 diabetes." (PMID 37664540, 2023). "Where NGS was employed, the monogenic diabetes diagnostic yield increased by around 30% compared to Sanger sequencing of GCK, HNF1A and HNF4A alone, and resulted in the (often unexpected) diagnosis of rare syndromic forms of diabetes, most commonly m.3243A>G." (PMID 37794142, 2023). "Considering our results, fasting- or diabetes-dependent induction of CAR is regulated by PPARα as well as HNF4α." (PMID 36835365, 2023). "Pathogenic variants in HNF1A (MIM: 142410), HNF4A (MIM: 600281), and GCK (MIM: 138079) account for >80% of all monogenic diabetes." (PMID 36257325, 2022). "The m.3243A>G mutation is the 4th most common cause of monogenic diabetes (8% of all monogenic cases) after mutations in GCK, HNF1A and HNF4A in patients with suspected MODY." (PMID 34789499, 2022). "Most HNF4α-related diseases have abnormal insulin secretion such as occurrence of diabetes mellitus (including Type I and Type II diabetes mellitus), while the underlying molecular mechanism remains elusive." (PMID 36249028, 2022). "Genes implicated in monogenic diabetes include several encoding transcription factors involved in pancreatic beta cell development (e.g. HNF1A, HNF1B, HNF4A, PDX1, GATA4, GATA6)." (PMID 35618782, 2022).
diabetes (continued). "The analysis revealed that GCK-MODY patients have a more similar metabolomic pattern to healthy individuals than to patients with other forms of diabetes (HNF4A-MODY, HNF1A-MODY and type 2 diabetes)." (PMID 35179657, 2022). "We comprehensively assess the penetrance and prevalence of pathogenic variants in HNF1A, HNF4A, and GCK that account for >80% of monogenic diabetes." (PMID 36257325, 2022). "Hepatic HNF4α expression is highly variable in humans, and HNF4α is markedly decreased in diabetes and NAFLD." (PMID 35614477, 2022). "MODY is monogenic diabetes caused by a single gene mutation of either HNF-1α, HNF-1β, HNF-4α, HNF-1β, glucokinase, PAK4, KLF11, neurogenic differentiation 1 (neuroD1), and insulin (INS)." (PMID 35956399, 2022). "Collectively, in stressed β-cells under diabetes, mitochondrial dysfunction caused by elevated UCP2 induced oxidative stress, resulting in activation of HNF4α and thus leading to the elevation of AldB expression." (PMID 35800776, 2022). "More than 20 causal genes have been linked to monogenic diabetes so far, the strongest evidence and highest prevalence having the transcription factors HNF1A, HNF4A, HNF1B and the GCK gene encoding the glucokinase enzyme." (PMID 34440499, 2021). "Heterozygous mutations in the genes encoding the transcription factors hepatic nuclear factor-4α and -1α (HNF4A and HNF1A, respectively) result in reduced insulin secretion and mutation carriers develop diabetes in childhood or early adulthood." (PMID 33569631, 2021). "Due to the progressive nature of HNF4A-MODY, patients are susceptible to diabetes-related complications." (PMID 33292863, 2020). "We report a UK-based economic evaluation of these realistic strategies to identify individuals with monogenic diabetes (defined here as mutations in GCK, HNF1A or HNF4A genes)." (PMID 32193268, 2020). "Hyperinsulinaemic hypoglycaemia in infancy and diabetes in later life have been reported in patients with HNF1A, HNF4A and ABCC8 mutations." (PMID 29739729, 2019). "Mutations in the HNF4A gene cause MODY1 and are associated with an increased risk of Type 2 diabetes mellitus." (PMID 30862908, 2019). "HNF4α has been reported to play a key role in controlling hepatic CES2 expression in diabetes, obesity, or NASH; thus, we also investigated and found that HNF1α positively regulates CES2 expression though much need to be done in the future (data not shown)." (PMID 31223625, 2019). "Our study suggests that successful treatment with diet/sulfonylurea alone was most likely in those with HNF1A/HNF4A-MODY who had a shorter duration of diabetes, healthy BMI and lower HbA1c at the time of genetic diagnosis." (PMID 30229274, 2018). "Phenotypically, patients with an HNF4A-MODY tend to have early-onset diabetes, microvascular complications, low triglyceride levels, increased birth weight, fetal macrosomia, and less commonly neonatal hyperinsulinemic hypoglycemia." (PMID 29998026, 2018). "Individuals with HNF1A/HNF4A-MODY are at increased, or at least the same, risk of developing diabetes-related complications compared with those with other diabetes subtypes." (PMID 30229274, 2018). "Improvement in glycaemic control among individuals with HNF1A/HNF4A-MODY is needed to prevent diabetes complications." (PMID 30229274, 2018). "RFX6 heterozygotes have reduced penetrance of diabetes compared to common HNF1A and HNF4A-MODY mutations (27, 70 and 55% at 25 years of age, respectively)." (PMID 29026101, 2017). "A total of 40 individuals with diabetes (1.8% of early onset sub-group and 0.6% of adult onset sub-group) were carriers of known pathogenic missense variants in the GCK, HNF1A, HNF4A, ABCC8, and INS genes." (PMID 29207974, 2017). "Among individuals with young onset and adult onset diabetes, 40 individuals (1.8% of subjects with early onset diabetes and 0.6% with late onset) were carriers of known pathogenic missense mutations in the GCK, HNF1A, HNF4A, HNF1B, ABCC8, and INS genes." (PMID 29207974, 2017).
diabetes (continued). "However, the limited number of samples included in this study does not qualify for a reliable quantitative marker analysis between the different S7 samples, hence we cannot exclude that HNF4A mutation or the diabetes status might moderately promote a certain cell fate." (PMID 28684784, 2017). "Positive C‐peptide is used to assess ongoing endogenous insulin secretion, and is likely to be present in patients with diabetes caused by HNF1A and HNF4A mutations." (PMID 27330718, 2016). "Mutation p.T130I was associated with both early-onset and late-onset diabetes and caused downregulated HNF4A expression, whereas HNF1A polymorphisms p.I27L and p.S487N were associated with the age of diagnosis of diabetes." (PMID 26981542, 2016). "Few examples include PPARG mutation in familial partial lipodystrophy (FPLD3), INSR in Donahue syndrome and Type A insulin resistance, HNF4A in Maturity-Onset Diabetes of Young (MODY1), and INS in Diabetes-type hyperglycemia and hyperinsulinemia." (PMID 27376154, 2016). "Of the eight probands and five relatives with diabetes seen in our center diagnosed with HNF1A or HNF4A diabetes, three were prescribed a sulphonylurea drug at the time of molecular testing." (PMID 27330718, 2016). "Of these, 36 probands were seen in the adult diabetes clinic, and were tested for one or more of the monogenic diabetes genes GCK, HNF1A, HNF4A and HNF1B or the mitochondrial m.3243A>G mutation." (PMID 27330718, 2016). "The PAD gene list relates to a diverse set of human diseases, including cardiovascular (LMNA, MYH7), cystic fibrosis (CFTR), diabetes (HNF4A, IRS1) and migraine (ATP1A2)." (PMID 25611800, 2015). "The aim of this study was to identify, at the level of mRNA, potential sex- and diabetes-dependent changes of Oats, Octs, ATP-dependent efflux transporters, and the transcriptional regulators, Hnf1α, Hnf1β, and Hnf4α." (PMID 25710042, 2015). "Although apparently MODY and diabetes seem unrelated to PD, recently some researchers proved a relation between diabetes and PD and, even more interestingly, they discovered that HNF4A is responsible for the disregulation of several PD biomarkers." (PMID 25541727, 2014). "The combined efficacy of MEDICA analogs in treating diabetes, while mimicking (n-3) PUFA activity in suppressing HNF-4α transcriptional activity, prompted our interest in probing their efficacy in suppressing carcinogen-induced diabetes-promoted CRC." (PMID 25375205, 2014). "Because HNF4α is a known master regulator of metabolic gene expression in the liver and is strongly associated with MODY forms of diabetes, we focused in more detail on the relationship between TCF7L2 and HNF4α at the molecular and genomic level." (PMID 25414334, 2014). "Heterozygous inheritance of an HNF4A mutation results in a similar phenotype to the patients with HNF1A mutations and accounts for approximately 5–10% of all cases of monogenic diabetes." (PMID 23766565, 2013). "HNF4A, a transcription factor regulated by TGF-beta signaling, is associated with diabetes and HCC, but has only recently been linked to intestinal tract pathology including ulcerative colitis and Crohn’s disease." (PMID 23822816, 2013). "The genes that code for transcription factors associated with monogenic diabetes include HNF1A, HBF1B, HNF4A, PDX1, NEUROD1, and some others." (PMID 22996131, 2012). "Our study was focused on pancreatic ß-cells because HNF4α is one of the culprit gene products for a dominantly inherited form of diabetes, MODY, mainly characterized by the defect in insulin secretion from ß-cells." (PMID 22952853, 2012). "Our data my also provide insight into the mechanism by which mammalian HNF4α protects against diabetes." (PMID 22511885, 2012). "In our previous study, we found that HNF4α was sensitive to plasma insulin level and was downregulated by SREBPs in hyperinsulinemia diabetes and hepatic SREBPs were downregulated by HNF4α overexpression in mice (unpublished data)." (PMID 22190905, 2011).